KRAS (KRas proto-oncogene, GTPase)
Diseases named in the same sentence as KRAS in open-access papers (continued):
Sharing a sentence is not in itself a finding about the gene and the disease.
inflammatory bowel disease (6 papers, 2017 to 2025). A spectrum of small and large bowel inflammatory diseases of unknown etiology. "Our patient’s case illustrates this sporadic pattern well, as he had no family history of cancer, he tested negative for KRAS, NRAS, BRAF, and PIK3CA mutations, and he showed no signs of inflammatory bowel disease." (PMID 41487588, 2025). "In addition, KRAS mutations have been reported in 24% to 50% of inflammatory bowel disease (IBD)–associated SBAs,6,8,29 suggesting that the lack of KRAS point mutations is more likely related to the SB-PCC histology than to IBD-related etiology." (PMID 36812376, 2023).
large cell lung cancer (6 papers, 2015 to 2023). "EGFR (15.8%) and KRAS (21.1%) mutations were present in a considerable proportion in lung large cell carcinoma." (PMID 26486077, 2015).
linear nevus sebaceous syndrome (6 papers, 2015 to 2023). "Almost simultaneously, it was demonstrated that nevus sebaceous and linear sebaceous nevus syndrome are also caused by postzygotic HRAS and KRAS mutations." (PMID 34208656, 2021).
lymphedema (6 papers, 2022 to 2025). Excess fluid collection in tissues, causing swelling. "Activating KRAS mutations have been identified recently in LM patients with lymphedema, chylous ascites, or life-threatening chylothorax." (PMID 40236167, 2025). "We identified 4 individuals with CCLA, lymphedema, and microcystic lymphatic malformation due to pathogenic, mosaic variants in KRAS." (PMID 37154160, 2023). "Moreover, KRAS somatic mutations have been reported in two adult patients diagnosed with PWS who also presented unusually severe lymphedema and microcystic lymphatic anomalies." (PMID 35740480, 2022). "Activating KRAS mutations were found in patients with CCLA and PWS associated with lymphedema and microcystic LM." (PMID 38488007, 2024). "Additionally, activating KRAS pathogenic variants have also recently been described as a cause of aberrant vascular development, vascular malformation, and lymphatic anomalies including lymphedema, chylothorax, macrocystic lymphatic malformation, lymphangiectasia, and Gorham-Stout disease." (PMID 37154160, 2023). "In this study, we verify mosaic, activating KRAS pathogenic variants as a cause of CCLA and lymphedema and report what we believe is the first microcystic lymphatic malformation caused by mosaic, activating KRAS pathogenic variants." (PMID 37154160, 2023). "Notably, in both cases of co-occurring lymphedema and LM associated with CCLA or PWS, the disease was attributed to a somatic mutation in KRAS." (PMID 38488007, 2024).
medulloblastoma (6 papers, 2008 to 2023). A malignant, invasive embryonal neoplasm arising from the cerebellum. "The selected ptf1a promoter also drives conditional KRASG12D expression in cerebellum; thus, we were able to assess KRAS activity during the early stages of cerebellar development by obtaining a concomitant model of putative pediatric medulloblastoma (MDB)." (PMID 24878567, 2014). "In addition, we also enriched some signaling pathways that have been widely reported to affect the metastasis of medulloblastoma, such as PI3K/AKT, TGF-beta, MYC, Notch, KRAS signaling pathway." (PMID 36303547, 2022).
metabolic syndrome (6 papers, 2014 to 2024). A cluster of metabolic risk factors for CARDIOVASCULAR DISEASES and TYPE 2 DIABETES MELLITUS. "The difference between the two subsites may reflect diversities in tumour microenvironment (TME), with a TME in distal colon favoring KRAS related tumor progression in patients with serum dyslipidemia." (PMID 32594310, 2020).
mismatch repair deficiency (6 papers, 2021 to 2024). "KRAS mutations (KRASmut), PIK3CAmut, BRAFmut, and mismatch repair deficiency (dMMR) have been associated with the Warburg-effect." (PMID 35546360, 2022). "The remaining 10–15% of KRAS wild-type (KRAS-WT) tumors harbor frequent genomic events that can be targetable, such as homologous recombination genes, including BRCA1/2, PALB2, mismatch repair deficiency (dMMR), BRAF mutations/fusions, NRG1 and NTRK fusions, and other less common mutations." (PMID 39062863, 2024). "First, it has been suggested that mutations in KRAS, PIK3CA, and BRAF drive metabolic reprogramming toward the Warburg-effect, and we have shown previously that MMR deficiency is associated with presence of the Warburg-effect." (PMID 35546360, 2022).
neuroendocrine tumors (6 papers, 2018 to 2022).
ovarian endometriosis (6 papers, 2017 to 2025). A non-neoplastic disorder characterized by the growth of endometrial tissue in the ovaries. "Another study revealed that somatic mutations specifically in cancer-associated genes were observed in 4% of ovarian endometriosis samples, including KRAS p.G12V and PPP2R1A p.S256F along with two ARID1A nonsense mutations, p.Q403 * and p.G1926 *." (PMID 40364006, 2025). "Although 43% of ovarian endometriosis cases harbor KRAS mutations, the frequency of malignant transformation of ovarian endometriosis is 0.5–1%." (PMID 33809880, 2021). "Interestingly, KRAS mutation is the most frequent event occurring in ovarian endometriosis, DE, and IE." (PMID 33809880, 2021). "Furthermore, our recent study has reported that KRAS G12V mutant allele expression was associated with inflammation in ovarian endometriosis." (PMID 33809880, 2021). "This hypothesis is consistent with the findings that KRAS-mutated cells are able to clonally expand inside ovarian endometriosis." (PMID 33809880, 2021). "Our previous study clarified that PIK3CA, ARID1A, KRAS, FBWX7, and PPP2R1A are also frequently mutated in ovarian endometriosis." (PMID 38067342, 2023). "By multiregional sequencing, we demonstrated that epithelial cells with cancer-associated mutations such as oncogenic PIK3CA and KRAS mutations clonally expand in ovarian endometriosis without cancer." (PMID 33809880, 2021).
pancreatic NECs (6 papers, 2020 to 2025). "In GEP-NECs, KRAS mutations are reported at a similar frequency as in conventional cancers arising at the same sites: KRAS genes are frequently mutated in colorectal and pancreatic NECs, while they are less common in esophageal NECs." (PMID 37422534, 2023). "In a report on pancreatic NEC given platinum-treatment, RR was significantly higher for RB1 loss and/or KRAS mutation." (PMID 38909137, 2024).
renal fibrosis (6 papers, 2019 to 2025). A final common manifestation of a wide variety of chronic kidney diseases characterized by glomerulosclerosis and tubulointerstitial fibrosis. "In conclusion, our study demonstrates that circRNA_30032 promotes TGF-β1-induced and UUO-induced renal fibrosis via miR-96-5p/HBEGF /KRAS axis and p38MAPK signaling pathway." (PMID 33973871, 2021). "In a UUO mouse model and in TGF-beta-stimulated mouse renal tubular epithelial cells, circRNA_30032 was significantly upregulated and exacerbated renal fibrosis via the miR-96-5p/HBEGF/KRAS signaling pathway." (PMID 35222519, 2021). "Overall, our data demonstrated that circRNA_30032 promoted renal fibrosis via miR-96-5p/ HBEGF/KRAS axis." (PMID 33973871, 2021). "Previous studies have demonstrated that both HBEGF and KRAS promote renal fibrosis." (PMID 33973871, 2021). "Moreover, circRNA_30032 silencing suppressed UUO-induced renal fibrosis via the miR-96-5p/HBEGF /KRAS axis." (PMID 33973871, 2021). "Moreover, knockdown of circRNA_30032 attenuated UUO-induced renal fibrosis by regulating the miR-96-5p/ HBEGF/KRAS axis." (PMID 33973871, 2021). "In the current study, we demonstrated that circRNA_30032 mediated TGF-β1-induced renal fibrosis in BUMPT cells and in kidney tissues of UUO-induced mice by sponging miR-96-5p and inducing the expression of HBEGF and KRAS." (PMID 33973871, 2021). "CircRNA_30032 silencing significantly reduced renal fibrosis in UUO model mice by increasing miR-96-5p levels and decreasing levels of HBEGF and KRAS." (PMID 33973871, 2021). "Therefore, we speculate that a synergistic mechanism between the KRAS and TGF-β pathways may contribute to the progression of renal fibrosis in CKD patients." (PMID 40653823, 2025).
small intestinal tumors (6 papers, 2008 to 2021). "More importantly, in ApcMin/KRAS V12 double transgenic mice that had a great tendency to develop small intestine tumors, deleting one allele of Klf5 led to a 92% reduction in tumor burden." (PMID 33923166, 2021).
tubulovillous adenoma (6 papers, 2007 to 2022). An epithelial neoplasm morphologically characterized by the presence of a villous and a tubular architectural pattern. "In this context, a multi-omics study established that the HT-29 cell line in the CMS3 metabolic type is related to tubulovillous adenomas with serrated features and more prevalent KRAS mutations." (PMID 36432565, 2022). "A recent study reported that serrated tubulovillous adenomas (sTVAs), which are a type of TVA, represent an important precursor of KRAS mutated, CIMP-low/negative and MSS CRCs." (PMID 29435136, 2018).
uveal melanoma (6 papers, 2005 to 2026). A melanoma derived from melanocytes of the uveal tract. "We thus screened for activating mutations in the NRAS, HRAS, KRAS and BRAF genes in uveal melanoma cell lines and primary uveal melanomas." (PMID 15928660, 2005). "Mutations of NRAS, KRAS, and HRAS occur in 10–25%, 2%, and 1% of non-uveal melanoma, respectively, including those arising both on sun-exposed and sun-unexposed skin, mucosal, and acral melanomas; in contrast, RAS mutations are rarely observed in uveal melanomas." (PMID 30934534, 2019). "Previous study demonstrated that the activation of KRAS-ERK signaling can promote development and migration of uveal melanoma cells." (PMID 35422861, 2022).
acute pancreatitis (5 papers, 2012 to 2024). An acute inflammatory process that leads to necrosis of the pancreatic parenchyma. "Conversely, downregulated DEGs in the Pdx1-Ehmt2fl/fl and P48-Ehmt2fl/fl acute pancreatitis models were only significantly enriched for networks that signal KRAS down." (PMID 38948355, 2024). "In an experimental study in mice, the expression of oncogenetic KRAS was found to be related to acute pancreatitis, which may develop into PaCa." (PMID 36291775, 2022). "We next examined whether loss of κB-Ras would also alter ADM in response to cerulein-induced acute pancreatitis, independently of oncogenic KRas expression." (PMID 32641778, 2020).
ampullary adenocarcinoma (5 papers, 2016 to 2024). "In examining localized pancreatic and ampullary adenocarcinomas, it was found that KRAS mutations were present in 80% of PDAC and 67% of ampullary adenocarcinomas." (PMID 38666907, 2024). "Notably, KRAS mutations served as an independent prognostic biomarker for shorter overall survival in chemotherapy-naive patients with ampullary adenocarcinoma." (PMID 38666907, 2024).
Burkitt lymphoma (5 papers, 2016 to 2026). A rare form of malignant mature B-cell non-Hodgkin lymphoma.
Cachexia (5 papers, 2016 to 2022). Severe weight loss, wasting of muscle, loss of appetite, and general debility related to a chronic disease. "The high prevalence of cachexia in PDAC is associated with distinct metabolic effects mediated by tumor created environments, including KRAS mutations, pro-cachexia mediators, and alteration in pancreas and liver." (PMID 36465353, 2022). "Secondly, we were lacking in some data, such as C-reactive protein, cachexia, sarcopenia, and KRAS mutation status, which were essential to survival." (PMID 35719977, 2022). "Our study showed that the presence of a KRAS mutation in the tumor correlated with the development of cachexia, whereas EGFR mutation was not significantly correlated with cachexia." (PMID 27485414, 2016).
cystadenoma (5 papers, 2012 to 2024). A benign or borderline cystic epithelial neoplasm arising from the glandular epithelium. "It has also been reported that a small proportion of these cystadenomas become clonal and that KRAS or BRAF mutations in some of these clonal cystadenomas lead to the development of SBTs, which are the precursors of LGSOCs." (PMID 35326657, 2022). "Mutations of KRAS and BRAF are detected in both SBTs and cystadenoma epithelium adjacent to SBTs." (PMID 24868556, 2014). "Concordantly, other research has correlated KRAS and CDKN2A pathway alterations withmucinous cystadenomas and borderline tumors." (PMID 39040449, 2024).
duodenal adenocarcinoma (5 papers, 2018 to 2025). A carcinoma that arises from glandular epithelial cells of the duodenum. "Also, liquid biopsy, which has been attracting attention as a noninvasive method in recent years, could be used to monitor treatment resistance in duodenal adenocarcinoma by targeting KRAS mutations." (PMID 34797780, 2021). "Therefore, KRAS mutation in advanced-stage duodenal adenocarcinoma might have specific implications, and active treatment might be important for preventing advanced-stage neoplasia." (PMID 34797780, 2021). "In univariate analysis of primary deaths from duodenal adenocarcinoma, TNM stage II or higher, undifferentiated, KRAS mutations, gastric phenotype, intestinal phenotype, and PD-L1 status were significant factors." (PMID 34797780, 2021). "KRAS mutation was an independent factor for primary mortality in nonampullary duodenal adenocarcinoma, regardless of TNM stage (stage II or higher)." (PMID 34797780, 2021). "There were cases of duodenal adenoma and early-stage duodenal adenocarcinoma with KRAS mutation but without primary mortality." (PMID 34797780, 2021). "Only KRAS mutation was a significant prognostic factor in primary sporadic nonampullary duodenal adenocarcinoma in cases in which TNM stage was considered." (PMID 34797780, 2021). "KRAS status might also be useful when considering adjuvant or neoadjuvant chemotherapy for duodenal adenocarcinoma, although the effect is still unclear at present." (PMID 34797780, 2021). "Although further molecular biological analysis is required to investigate the usefulness of candidate genes other than KRAS and BRAF, assessing KRAS mutation could be a very useful tool for treating sporadic nonampullary duodenal adenocarcinoma." (PMID 34797780, 2021). "However, among the 93 patients with duodenal adenocarcinoma, there were 23 patients with KRAS mutation, and they were significantly different from the 70 patients without KRAS mutation in terms of sex (P = 0.01), BRAF mutation (P < 0.01), and mucin phenotype (P = 0.01)." (PMID 34797780, 2021).
embryonal carcinoma (5 papers, 2021 to 2025). A non-seminomatous malignant germ cell tumor characterized by the presence of large germ cells with abundant cytoplasm resembling epithelial cells, geographic necrosis, high mitotic activity, and pseudoglandular and pseudopapillary structures formation. "A total of 50.0% (1/2) pure teratomas had a KRAS missense mutation p.G12C, and the only pure embryonal carcinoma had a KRAS copy number gain (TGCT-18)." (PMID 41009531, 2025). "The KRAS mutation was also recurrent, but mutations occurred less frequently than with KIT, with two KRAS mutations in codon 12 (one in embryonal carcinoma and one in mixed yolk sac-dysgerminoma tumors)." (PMID 37296950, 2023).
endometrioid endometrial carcinoma (5 papers, 2010 to 2023). "KRAS mutations were detected in endometrial hyperplasias at a similar rate to that observed in endometrioid endometrial carcinomas, suggesting that KRAS mutations are early events in endometrial carcinogensis." (PMID 20368795, 2010). "As we and others have previously shown in primary endometrioid endometrial carcinomas (EECs), we found that multiple members of the PI3K pathway and sometimes KRAS were mutated in the same cell lines, including concomitant mutations." (PMID 29426295, 2018). "Although KRAS mutations are not unique to MLA and can be identified in 20–30% of the endometrial endometrioid carcinoma, with the additional use of histological features and immunophenotypes characteristic of MLA, the identification of KRAS mutations can confirm MLA diagnosis." (PMID 37626765, 2023). "Furthermore, none of the five main alterations of endometrioid endometrial carcinoma (mutations of PTEN, PIK3CA, KRAS, and CTNNB1 genes and MSI) plays a major role in non-endometrioid endometrial carcinoma." (PMID 20368795, 2010).
fibrosis (5 papers, 2009 to 2024). the formation of excess fibrous connective tissue in an organ or tissue in a reparative or reactive process. "The results for the TGF-β dataset and the Fibrosis dataset are presented below while the results for the TCDD and KRAS datasets are presented in Supplementary Results." (PMID 38280860, 2024).
Hepatitis (5 papers, 2016 to 2025). Inflammation of the liver. "A recent pharmacovigilance study found that when targeted therapies are combined with checkpoint inhibitors, KRAS‐directed agents were most strongly associated with the development of hepatitis, with a significant reporting odds ratio of 3.03." (PMID 39842846, 2025). "The frequencies of KRAS and IDHs mutations, which are associated with poor disease-free survival, were significantly higher in hepatitis-negative cases." (PMID 36672443, 2023). "Similarly, a molecular study on 97 liver cancers with biliary phenotype reported a higher recurrence rate of KRAS (20%) and IDH1/2 (20%) mutations in hepatitis-negative patients, compared to hepatitis-positive patients." (PMID 37174616, 2023).
hereditary nonpolyposis colorectal cancer (5 papers, 2018 to 2024). "Hereditary nonpolyposis colorectal cancer (HNPCC) involves the mutator phenotype/mismatch repair pathway with germline mutations in the hMLH1, hMSH2, hMSH6, or PMS2 genes, and also presents with KRAS mutations." (PMID 30544946, 2018).